IL6 (interleukin 6)
Diseases named in the same sentence as IL6 in open-access papers (continued):
Sharing a sentence is not in itself a finding about the gene and the disease.
Sepsis (continued). "Previous studies have shown that TNF and IL-6 are the cytokines most strongly associated with sepsis." (PMID 29257842, 2017). "A decrease in blood Lac level ≥10% is associated with lower levels of plasma IL-6 and better brain mitochondrial respiration during the first 6 h of resuscitation after experimental sepsis induced by fecal peritonitis." (PMID 28499395, 2017). "An observational, prospective and multicenter study including severe septic patients was undertaken and serum IL-6 levels at severe sepsis diagnosis and IL-6 promoter polymorphism (-174 G/C) were determined." (PMID 27834822, 2016). "IL-6 is directly related to the risk of death in patients with sepsis and IL-6 blockade protected against this disease, suggesting that huCETP animals are resistant to sepsis induced death due to lower plasma concentrations of IL-6 in 48 hours." (PMID 27293313, 2016). "IL-6 is also associated with CLP induced sepsis, and it was reported that selective blockade of IL-6 transsignaling improves survival rate." (PMID 28042205, 2016). "In line, IL-6 is known to be a clinically suitable biomarker for sepsis, and Waage and coworkers observed high levels of IL-6 and its association with sepsis in patients with meningococcal infection." (PMID 27532003, 2016). "Data for the IL6 genotype GC-CC were also supported by its association with further worsening of critical illness from severe sepsis to septic shock in pneumonia patients." (PMID 27725770, 2016). "In sepsis blockade of either C5aR 1, C5aR2 or C5a were associated with decreased serum levels of IL-6." (PMID 27437704, 2016). "Severe sepsis/septic shock were associated with the IL6 rs1800795 GC-CC and IL10 rs1800896 G/G genotypes." (PMID 27725770, 2016). "We selected plasma biomarkers, measured at ICU admission, known to be associated with sepsis outcomes, including interleukin (IL)-6, IL-8, granulocyte colony-stimulating factor (G-CSF), angiopoietin-2 (ANG2), and IL-1 receptor antagonist (IL1RA)." (PMID 27431667, 2016). "Underlying the multiple organ failure was a severe SIRS/sepsis response, despite initial leukopenia, with extremely high levels of IL-6 (20,000 pg/mL) and IL-8 (24,656 pg/mL), exudative alveolar edema, systemic vasoplegia, and marked capillary leak syndrome." (PMID 26885411, 2016). "The influence of IL-6 promoter polymorphism (-174 G/C) on sepsis risk and sepsis mortality has been addressed in some studies." (PMID 27834822, 2016). "In CAP patients, the IL6 rs1800795-C allele was associated with severe sepsis/septic shock/severe systemic inflammatory response, while the IL10 rs1800896-A allele protected against the development of these critical conditions." (PMID 27725770, 2016). "According to our findings, it has been described that increased serum levels of IL-5 and IL-6 were associated with reduced microbial clearance and higher mortality rates in sepsis." (PMID 26975045, 2016). "More studies in Asian population are needed to estimate the effect of IL-6–174G/C polymorphism on sepsis risk." (PMID 25734339, 2015). "Procalcitonin (PCT), interleukin-6 (IL-6), and tumor necrosis factor-α have previously been used as diagnostic markers for sepsis." (PMID 26623644, 2015). "In particular, plasma levels of IL-6, IL-8, and G-CSF have been previously shown to be associated with mortality in sepsis in humans." (PMID 26492036, 2015). "The distribution of haplotypes of TGF-β and IL-6 were also associated with sepsis susceptibility and outcome." (PMID 26561011, 2015). "In our meta-analysis, we evaluated the association between IL-6–174G/C polymorphism and sepsis under the allele comparison, codominant, recessive and dominant model, respectively." (PMID 25734339, 2015). "Although a statistical association was found between IL-6–174G/C polymorphism and sepsis mortality under the recessive model (for CC vs. GC/GG: OR = 1.92, 95%CI 1.06–3.84, P = 0.03), this was not maintained after Bonferroni’s correction." (PMID 25734339, 2015).
Sepsis (continued). "To better understand the role of IL-6-174G/C polymorphism in sepsis, we conducted a comprehensive meta-analysis." (PMID 25734339, 2015). "After removing the study, the heterogeneity decreased notably and there was a significant association between IL-6–174G/C polymorphism and sepsis-related mortality under the codominant model (for CC vs. GG: OR = 3.32, 95%CI 1.48–7.43, P = 0.004)." (PMID 25734339, 2015). "Although the pathophysiological mechanisms underlying sepsis are unclear, pro-inflammatory cytokines such as IL-6 and IL-1β, which are involved in the immune response, are clearly closely linked to the pathogenesis of sepsis." (PMID 25888255, 2015). "Although there was a statistically significant association between IL-6-174 G/C polymorphism and sepsis-related mortality under the recessive model, the significance did not exist after Bonferroni’s correction." (PMID 25734339, 2015). "There was a statistical association between IL-6–174 G/C polymorphism and sepsis-related mortality under the recessive model (for CC vs. GC/GG: OR = 1.92, 95%CI 1.06–3.84, P = 0.03)." (PMID 25734339, 2015). "To date, about twenty studies have been reported to evaluate the association between IL-6–174G/C polymorphism and sepsis." (PMID 25734339, 2015). "Our study shows that males with sepsis have a 70% greater mortality rate, and mortality is associated with a higher IL-6 plasma level." (PMID 26649014, 2015). "Recently, increasing studies have been conducted to evaluate the association between IL-6–174G/C polymorphism and sepsis." (PMID 25734339, 2015). "Previous studies revealed that high IL-6 level was associated with increased severe sepsis mortality and risk." (PMID 25734339, 2015). "The study points out the importance of interactions among the BPI, LBP, TLR, HSP 70 and IL-6 polymorphisms and also highlights the relevance of the combination of gene polymorphisms to sepsis outcome." (PMID 24383711, 2014). "Multivariate risk factor analysis identified hematological diseases (odds ratio (OR), 11.71), ≥15 % BM macrophages (OR, 9.42), sepsis (OR, 7.77), and high serum IL-6 levels (OR, 1.00) as independent risk factors for HHH." (PMID 24852692, 2014). "Similar to the previous triplet, the combination of major homozygosity for BPI, TLR and IL-6 SNPs was associated with high risk of sepsis development (P <0.001)." (PMID 24383711, 2014). "Specific combinations of common homozygosity for BPI, LBP, TLR, HSP 70 and IL-6 variants were typical within the septic group and were associated with a high risk of sepsis development." (PMID 24383711, 2014). "Asiaticoside has protective effects against sepsis-induced acute kidney injury, which is most likely associated with the inhibition of IL-6 in serum and the iNOS protein in kidney tissues." (PMID 24667059, 2014). "Cox regression analysis showed that cardiovascular diseases, IL-6 and eHSPA12B were risk factors for mortality in patients with severe sepsis." (PMID 24977412, 2014). "Based on the presented results, a single or double biomarker combination (for example, presepsin and IL-6) for diagnostic and prognostic assessment appears to be useful in patients with severe sepsis or septic shock being treated on a medical ICU." (PMID 25190134, 2014). "In contrast, some studies, especially by Pickler and colleagues, reported that high levels of TNF-α, IL-6, and IL-1 are often associated with profiles of sepsis in neonates." (PMID 25614712, 2014). "Based on previous research, it was shown that homozygous mutant mice for Bag4 have enhanced cytokine responses and increased IL-6 production following TNF challenge i.e. septic shock (Kp is a major pathogenic cause of sepsis)." (PMID 25283706, 2014). "Presepsin levels revealed valuable diagnostic capacity to diagnose severe sepsis and septic shock at days 1, 3 and 8 (range of diagnostic area under the curves (AUC) 0.72 to 0.84, P = 0.0001) compared to IL-6, PCT, CRP and WBC." (PMID 25190134, 2014).
Sepsis (continued). "While IL-6 and IL-8 levels have been shown to be elevated in sepsis and associated with severity and outcome, they have not been found to be superior to PCT as biomarkers." (PMID 24772418, 2014). "Plasma levels of IL-6 are elevated in patients with sepsis and high IL-6 concentrations are associated with increased mortality." (PMID 24383711, 2014). "High levels of TNF and IL-6 are associated with septic shock, however, the levels in C. albicans-infected Lat2−/− mice are much lower than those in murine sepsis models making it an unlikely cause for the increased mortality." (PMID 23675302, 2013). "In the current study, we sought to evaluate the serum levels of IL-6, 8 and 10 as early diagnostic markers in late neonatal infection (definitive infection and clinical sepsis) and their relationship to clinical outcomes." (PMID 24570828, 2013). "Combined high levels of IL-10 and IL-6 are associated with a very high risk of death in sepsis patients." (PMID 23437050, 2013). "In a recent study performed in rats with polymicrobial sepsis, treatment with hyperoncotic albumin attenuates hepatic injury in association with reduced plasma levels of IL-1β, IL-6, liver enzymes, and O2- concentrations." (PMID 23548047, 2013). "Increased IL-6 production is a hallmark of many human chronic inflammatory states, including sepsis, rheumatoid arthritis (RA), and inflammatory bowel disease (IBD)/colitis." (PMID 22937006, 2012). "High plasma IL-10, MIF and IL-6 levels have been associated with severity and a poorer outcome in sepsis and were chosen for the present study." (PMID 22701553, 2012). "Key pro- and anti- inflammatory mediators like IL-1α, MIP-1β, RANTES, CXCL-1, IL-6 and IL-10, implicated to play a role in sepsis were up-regulated at both the early and late time points." (PMID 23009705, 2012). "An IL-6 concentration ≥ 67.1 pg/ml at days 1–2 was highly associated with the development of sepsis and with the need of vasoactive support during the two first days following trauma (p<.0001)." (PMID 22431998, 2012). "Proinflammatory cytokines play a critical role in ALI and ARDS: persistently elevated levels of proinflammatory cytokines such as TNF-α and IL-6 are associated with worse outcome in patients with ALI or sepsis." (PMID 23199346, 2012). "Of specific interest, both IL-6 and IL-10 levels, which strongly correlate with survival outcome in sepsis, were significantly attenuated in SRA deficiency." (PMID 23071440, 2012). "Increased production of the pleiotropic cytokine IL-6 is the hallmark of inflammatory diseases and sepsis." (PMID 22606320, 2012). "The increased concentrations of IL-1β, IL-6, IL-8, and G-CSF 7 days after combined injury were caused by the combined injury-induced sepsis due to the bacterial entry from the broken GI barrier and the skin-wound site." (PMID 22686656, 2012). "Using CLP-induced sepsis model in mice, IL-6 blockade was shown to have protective effects on sepsis, which are linked to reduced C5a receptor expression in lung, liver, kidney, and heart." (PMID 23233853, 2012). "• rhDNase therapy is associated with elevated neutrophil counts in sepsis-related organs, enhanced tissue damage and higher levels of IL-6 in the circulation early after CLP in vivo." (PMID 22835277, 2012). "This study is the first to address the combined measurement of hepcidin, IL-6 and Hb levels in patients and shows that hepcidin probably plays a role in sepsis-associated anemia." (PMID 21219610, 2011). "This further underlines that IL-6 & TNF-α are involved in the pathogenesis of sepsis but that they cannot be considered independent markers, based on our analyses." (PMID 22220196, 2011). "Our results showed that a tag SNP rs5743867 in TOLLIP, which influences the expression of TOLLIP mRNA and the production of TNF-α and IL-6, was significantly associated with susceptibility to sepsis." (PMID 21219635, 2011).
Sepsis (continued). "Previously, measurement of IL-6 level enabled us to accurately predict individuals who were at significant risk of sepsis, so we also measured IL-6 concentrations." (PMID 23554654, 2010). "Although IL-6 has been implicated in the triggering process of sepsis and correlates with its severity, IL-1β has been associated with the degree of VILI." (PMID 20546573, 2010). "High plasma IL-6, IL-8, and IL-10 levels have recently been associated with increased mortality in human sepsis-related ARF." (PMID 20546598, 2010). "Sepsis caused a large increase in IL-6 in the serum, some of which likely accounted for the increased brain levels of IL-6." (PMID 19284588, 2009). "The analysis of cytokine levels measured at the onset of fever indicated that IL-6 and IL-8 are useful to define a possible group of patients with low risk of sepsis." (PMID 18321393, 2008). "We have also shown that CRP, lipopolysaccharide-binding protein (LBP), and IL-6 were better diagnostic markers for infection and sepsis than procalcitonin (PCT) in the same cohort of patients." (PMID 17346334, 2007). "IL-6 is a pro-inflammatory cytokine associated with the development of shock and mortality from sepsis." (PMID 16611358, 2006). "Our study data suggest that IL-6 with a cut off level of 25 pg/ml has the best diagnostic abilities in diagnosing sepsis." (PMID 16569262, 2006). "The association of an initial high level of IL-6 with organ failure and poor outcome is confirmed in patients with sepsis, after trauma and AAA patients." (PMID 16899122, 2006). "C-reactive protein, IL-6 and lipopolysaccharide-binding protein appear to be superior to procalcitonin as diagnostic markers for infection and sepsis in patients admitted to a Department of Internal Medicine." (PMID 16569262, 2006). "The IL-6 -174 G/C SNP has been inconsistently associated with altered risk for and outcome from sepsis in several studies." (PMID 16611358, 2006). "The association with IL-6 is noteworthy because this is a well-recognised marker of generalised inflammation, consistently elevated in patients with sepsis." (PMID 17002794, 2006). "For example, IL-6 increases the expression of the atrophy promoting ubiquitin ligase MuRF1 and promotes muscle loss following infusion, whereas IL-6 deficiency inhibits muscle loss in sepsis." (PMID 41592067, 2026). "Elevated IL-6 and procalcitonin levels were also independently associated with sepsis development." (PMID 41899132, 2026). "Therefore, the present study was designed to compare the temporal trends and diagnostic accuracy of PCT, CRP, and IL-6 in detecting early postoperative sepsis following lung decortication." (PMID 41281040, 2025). "In patients with thromboinflammatory disorders, such as sepsis, cancer-associated thrombosis, or autoimmune vasculopathies, the dysregulated production of IL-6 and FgDPs may simultaneously promote a hypercoagulable state and maladaptive thrombopoiesis." (PMID 41157266, 2025). "Therefore, markers such as white blood cell count, C-reactive protein, tumor necrosis factor, IL-1, and IL-6 are commonly used as auxiliary diagnostic indicators for sepsis in clinical practice." (PMID 40540505, 2025). "We tested whether kidney mitochondrial DNA (mtDNA) contributes to IL-6 release in sepsis-associated AKI via Toll-like receptor 9 (TLR9)." (PMID 41355794, 2025). "Moreover, elevated IL-6 levels associated with mortality in sepsis patients and IL-6’s efficacy in predicting sepsis mortality have demonstrated that it plays a direct role in human sepsis." (PMID 39955435, 2025). "Especially vascular-origin sepsis is reportedly linked to high mortality and elevated IL-6 levels." (PMID 40178612, 2025). "Older age and sepsis presence were both associated with higher IL-6 levels." (PMID 39935482, 2025). "Additionally, this study did not include key inflammatory biomarkers such as procalcitonin (PCT) and interleukin-6 (IL-6), which are closely associated with the pathophysiology of sepsis and delirium." (PMID 40668815, 2025).
Sepsis (continued). "Lactate and LDH were positively correlated with IL6, sE‐selectin, sICAM1, and sVCAM1, suggesting a possible association between lactate production and EC activation and the inflammatory response during sepsis." (PMID 39822760, 2025). "Furthermore, S100A9 is more sensitive than lactate and IL-6 for assessing mortality risk in sepsis, while its specificity is basically equivalent to that of lactate and IL-6." (PMID 40478888, 2025). "Therefore, the prognostic value of NUTRIC versus mNUTRIC in sepsis warrants further investigation, particularly regarding the potential role of IL-6 in enhancing risk stratification and clinical decision-making." (PMID 40823032, 2025). "Additionally, logistic regression analyses performed to identify risk factors for mortality revealed that sepsis and IL-6 emerged as independent risk factors." (PMID 41011807, 2025). "Interestingly, some studies suggest that an acute increase in IL-6 causes cardio-protection in the early stages of sepsis, decreases the process of apoptosis, and prevents oxidative damage." (PMID 39456869, 2024). "While IL-6’s prognostic value in sepsis is well documented, its diagnostic specificity is limited." (PMID 39768616, 2024). "Specifically, we have demonstrated that LBT exerts significant reductions in TNF-α, IL-6, and IL-1β levels while mitigating LPS-induced sepsis through the inhibition of genes associated with bacterial infection, cellular response to lipopolysaccharide, and cytokine-cytokine receptor interaction." (PMID 38799158, 2024). "Subgroups that combine IL-10 or IL-6 with NEWS or SIRS scores could further help identify high-risk individuals who may develop sepsis or require intensive care, allowing clinicians to further help guide treatment." (PMID 39212218, 2024). "Owing to the IL-6 trans-signaling, IL-6 may serve as the key cytokine to cause sepsis and cytokine storms by systemically targeting multiple tissues and organs." (PMID 38482486, 2024). "This study aimed to evaluate interleukin-6 (IL-6) and soluble triggering receptor expressed on myeloid cells-1 (sTREM-1) as potential biomarkers to improve diagnostic and prognostic capabilities in sepsis and SIRS." (PMID 39655134, 2024). "However, higher IL-6 one week after sepsis onset was also independently associated with mortality (HR 1.68, 95% C.I. 1.13–2.49, p = 0.01)." (PMID 38540711, 2024). "Elevated circulating levels of cytokines such as TNF-α, IL-1β, IL-6, IL-8, and IL-10 have been linked to increased morbidity and mortality in patients with sepsis, suggesting that their removal could be beneficial for treatment." (PMID 39766623, 2024). "Additionally, it decreased proinflammatory cytokine levels (TNF-α and IL-6), reducing the risk of sepsis from rapid bacterial lysis." (PMID 38622637, 2024). "However, it should be noted that HLA-DR downregulation correlates with reduced TNF, IL-6, and IL-1β release post- lipopolysaccharide (LPS) stimulation, increasing the risk of adverse events and death in sepsis." (PMID 38474403, 2024). "In addition, IL-6 has been shown to be a better diagnostic marker for sepsis compared to PCT and CRP." (PMID 39589972, 2024). "We analyzed whether the polymorphism was correlated with the cytokine expression of IL1β, IFNα2, IFNγ, TNF-α, IL-33, IL12p70, MCP-1, IL-6, IL-10, IL-17a, IL-18, or IL-23 to further investigate the effect of the polymorphism in sepsis patients." (PMID 38338680, 2024). "The cytokine interleukin-6 (IL-6) is important for the normal function of the immune system and also plays a pathogenic role in multiple diseases such as chronic inflammation, autoimmunity cancer, sepsis, and cardiovascular disease." (PMID 39518029, 2024). "It is known that on one hand, higher C-reactive protein and IL-6 levels have been associated more with Gram(−) bacteria than Gram(+) bacteria, inducing greater inflammation and thus raising concern regarding the treatment of Gram(−) sepsis." (PMID 38543060, 2024).